CTSD (cathepsin D)
Diseases named in the same sentence as CTSD in open-access papers (continued):
Sharing a sentence is not in itself a finding about the gene and the disease.
glioblastoma (9 papers, 2004 to 2025). The most malignant astrocytic tumor (WHO grade IV). "Meanwhile, inhibition of autophagy mediated by microRNA-17-5p, microRNA-93, or CTSD also enhances the response of glioblastoma cells to IR." (PMID 35152910, 2022). "Inhibiting CTSD increases the formation of autophagosomes but decreases the formation of autolysosomes, indicating that CTSD regulates the radiosensitivity of glioblastoma multiforme by affecting the fusion of autophagosomes and lysosomes." (PMID 35252181, 2022). "In glioblastoma multiforme, CTSD is highly expressed in radioresistant clones, which correlates to an increased level of autophagy." (PMID 35252181, 2022). "Cathepsin D is more frequently expressed in carcinomas than in connective tissue neoplasm such as glioblastoma; thus an inhibitory effect on cathepsin D can be excluded." (PMID 14997208, 2004). "In this study, the results showed that CTSD and IER3 were predominantly expressed in myeloid cells, high expression of AP1S1 was shown in glioblastoma cells, and YWHAG was mainly expressed in glioblastoma cells, oligodendrocytes, and myeloid cells." (PMID 35892430, 2022). "CTSD expression was highest in myeloid cells, high expression of AP1S1 was shown in glioblastoma cells, and YWHAG was mainly expressed in glioblastoma cells, oligodendrocytes, and myeloid cells, and IER3 was predominantly expressed in myeloid cells." (PMID 35892430, 2022). "The CTSD protein level is positively correlated with the autophagy marker LC3-II/I and negatively correlated with p62, In addition, knocking down CTSD with small interfering RNA increases radiosensitivity in glioblastoma cells." (PMID 35252181, 2022). "Moreover, CTSB and CTSD activities were also not affected by UTMD in IR-treated glioblastoma cells (P > 0.05)." (PMID 35152910, 2022).
tauopathy (9 papers, 2010 to 2025). Neurodegenerative disorders involving deposition of abnormal tau protein isoforms (tau proteins) in neurons and glial cells in the brain. "Furthermore, CTSD knockout in mice was associated with tauopathy, suggesting that CTSD also impacts abnormal Tau degradation." (PMID 39596030, 2024). "Increased levels of the lysosomal marker LAMP1 was detected in FAD and CBD, and in addition Cathepsin D was diffusely spread in the cytoplasm in all tauopathies suggesting an impaired lysosomal integrity." (PMID 26936765, 2016). "To investigate the role of lysosomal expansion and cathepsin D in tauopathies, we employed a genetically tractable in vivo approach." (PMID 20664788, 2010). "When cathepsin D was added to the rat brain homogenates, Tau degradation was observed, and depletion of cathepsin D advanced Tau-induced neurotoxicity in a Drosophila tauopathy model." (PMID 34445171, 2021). "Indeed, in tauopathy patients the lysosomal hydrolase CTSD shows a diffuse cytoplasmic localization, whereas in controls CTSD is observed in punctate structures corresponding to lysosomes." (PMID 32883341, 2020).
colon carcinoma (8 papers, 2012 to 2024). "Cathepsin D expression was low in the lung-adenocarcinoma-derived cell line (A549) and the colon-carcinoma-derived cell line (CaCO-2)." (PMID 37896224, 2023). "In colon cancer, activation of the Wnt/β-catenin signaling pathway can lead to increased levels of endogenous CTSD, and thus enhance the proliferation and invasiveness of colon cancer cells." (PMID 34552622, 2021). "Four prognostic hub genes associated with M2 macrophages in colon cancer were identified as follows: ANK4B, CTSD, TIMP1, and ZNF703, and the stability of these results was verified by different clustering methods and GSE39582 dataset." (PMID 34552622, 2021). "Here, we have used a proteomic approach to identify proteins in the secretome of L1-overexpressing CRC cells and studied the role of the increase in the aspartate protease cathepsin D (CTSD) in L1-mediated colon cancer development." (PMID 31497251, 2019).
heart failure (8 papers, 2013 to 2024). Inability of the heart to pump blood at an adequate rate to meet tissue metabolic requirements. "This profile includes beside the classical biomarker for heart failure, NT-proBNP, novel markers, which were driven from findings of experimental studies such as Cathepsin D, ADMA and miR-146a." (PMID 23812247, 2013). "Numerous studies on CTSD have shown its importance in the pathogenic mechanism of ischemic heart disease (ICD); the up-regulated expression of CTSD in ischemic cardiac muscle accelerates autophagic flux and inhibits cardiac remodeling and further heart failure." (PMID 36440001, 2022).
Sepsis (7 papers, 2015 to 2025). Sepsis is defined as life-threatening organ dysfunction caused by a dysregulated host response to infection. "This study aims to examine the association of LVV-hemorphin-7 (LVV-H7), cathepsin D, and cathepsin G with sepsis and shock in ICU patients." (PMID 39767696, 2024). "Furthermore, S. viridans sepsis was significantly associated with C4_RPL34, and CTSD may have an important role in this association." (PMID 37919720, 2023). "Patients with sepsis had a significantly higher expression of CTSD, GADD45A, MAPK14, MMP9, and VIM than normal health controls." (PMID 40184094, 2025). "Machine learning-based feature selection identified four robust biomarkers (APEX1, CTSD, SLC40A1, PIK3CB) associated with sepsis." (PMID 41041634, 2025). "We established a diagnostic model based on five key genes(SHKBP1,ICAM2,CTSD,SNX3, and SLC22A4), and Kaplan-Meier survival analysis revealed that SHKBP1 was significantly correlated with both the diagnosis and prognosis of sepsis." (PMID 41445732, 2025). "Using this model, we identified five key genes for constructing the sepsis diagnostic model: SHKBP1, ICAM2, CTSD, SNX3, and SLC22A4." (PMID 41445732, 2025). "A nomogram was constructed based on the expression profiles of APEX1, CTSD, SLC40A1, and PIK3CB, allowing for individualized prediction of sepsis risk." (PMID 41041634, 2025). "In C4_RPL34 cells in the context of S. viridans sepsis, genes co-expressed with CTSD were related to “Leukocyte migration,” “Intrinsic apoptotic regulation,” and “MYD88: MAL cascade initiation,” which may contribute to disease pathogenesis." (PMID 37919720, 2023). "Furthermore, RGS1, CCL3, and SOCS1 were connected to sepsis in animal studies, while for CTSD increased expression levels were observed in mice with induced septic shock." (PMID 25814982, 2015). "Violin plots depict the differential expression of CTSD, SLC40A1, PIK3CB (upregulated), and APEX1 (downregulated) in sepsis patients compared to the control group (***p < 0.001)." (PMID 41041634, 2025). "Five hub genes including CTSD, GADD45A, MAPK14, MMP9, and VIM were upregulated in patients with sepsis compared with normal controls in the GSE28750 (peripheral blood samples) and GSE64457 (neutrophil samples) datasets." (PMID 40184094, 2025). "The expression levels of CTSD (P < .001), GADD45A (P < .001), MAPK14 (P < .001), MMP9 (P < .001), and VIM (P < .001) were significantly higher in patients with sepsis than in normal healthy controls." (PMID 40184094, 2025). "Molecular docking analysis further indicated potential interactions between α-HB and key targets (APEX1, CTSD, SLC40A1, PIK3CB), providing insights into the molecular mechanisms of α-HB in sepsis." (PMID 41041634, 2025). "This study has identified 5 key genes – CTSD, GADD45A, MAPK14, MMP9, and VIM – that are significantly upregulated in sepsis patients compared to healthy controls." (PMID 40184094, 2025). "The sepsis group had significantly higher levels of free Hb (15.27 vs. 9.75 mg/dL; p < 0.001), cathepsin D (849.19 vs. 337.44 ng/mL; p < 0.001), and LVV-H7 (371.68 vs. 194.48 ng/mL; p < 0.001) than the non-sepsis group." (PMID 39767696, 2024). "Further multicenter prospective studies that enroll other non-sepsis control groups are needed to validate the clinical utility of cathepsin D, cathepsin G, and LVV-H7 in differentiating sepsis and septic shock." (PMID 39767696, 2024). "Significant differences were observed in CFH, cathepsin D, cathepsin G, and LVV-H7 levels between sepsis and non-sepsis groups." (PMID 39767696, 2024). "Several other targeted drugs were also identified in other types of sepsis, including nystatin targeting C1QA in Neisseria sepsis and dalfopristin targeting CTSD in Streptococcus viridans sepsis." (PMID 37919720, 2023). "Nevertheless, other hub genes such as ICAM1, CTSD, SNX3, and SLC22A4 also demonstrated biological relevance in sepsis and may contribute to disease pathogenesis through complementary mechanisms." (PMID 41445732, 2025).
Sepsis (continued). "Notably, APEX1, CTSD, SLC40A1, and PIK3CB were consistently selected by all three algorithms, underscoring their potential as robust marker genes for sepsis diagnosis and progression." (PMID 41041634, 2025). "CFH metabolites, including LVV-H7 and lysosomal enzyme cathepsin D and cathepsin G, were compared between the sepsis (definite and probable) and non-sepsis (possible sepsis) groups." (PMID 39767696, 2024). "Similarly, cathepsin D and LVV-H7 levels were significantly higher in the sepsis group (849 ± 703.1 and 371.7 ± 190.5 ng/mL, respectively) (p < 0.001) than in the non-sepsis (337.4 ± 141.1 and 194.5 ± 63.1 ng/mL, respectively) and control (220.4 ± 86.5 and 82.3 ± 6.4 ng/mL, respectively) groups." (PMID 39767696, 2024). "Therefore, the lysosomal enzyme (cathepsin G and cathepsin D), CFH metabolites (LVV-H7), and angiotensin II may act as different indicators to guide clinical infection outcomes, including sepsis, shock, or septic shock." (PMID 39767696, 2024).
breast tumors (6 papers, 1995 to 2014). "In patients, higher levels of Cathepsin D in the primary breast tumor correlate with increased incidence of metastasis and poorer disease prognosis." (PMID 24976340, 2014). "Cathepsin D expression was observed in both epithelial and stromal cells of prostate and breast tumors, whereas normal tissues were largely devoid of anti-cathepsin D antibody staining (data not shown)." (PMID 17183660, 2006). "We have analysed 2810 cytosolic extracts obtained from human primary breast tumours for cathepsin-D expression, and have correlated their levels with prognosis." (PMID 9888472, 1999).
coronary heart disease (6 papers, 2021 to 2025). "The expression levels of members of the cathepsin family (CTSD/CTSB) were up-regulated in patients with coronary heart disease." (PMID 36959587, 2023). "A study showed that upregulation of cathepsin D protected against cardiac malfunction by which promoted myocardial autophagic flux in an ischemic heart disease model." (PMID 33445607, 2021). "In this study, to better understand the mechanism of CTSD/CTSB in sudden coronary heart disease death, we also analyzed the TF-mRNA-miRNA relationship to obtain the co-regulatory network." (PMID 33964876, 2021).
frontotemporal dementia (6 papers, 2019 to 2025). Frontotemporal dementia (FTD) comprises a group of neurodegenerative disorders, characterized by progressive changes in behavior, executive dysfunction and language impairment, as a result of degeneration of the medial prefrontal and frontoinsular cortices. "Significantly higher levels of cathepsin D were found in patients with AD than in patients with frontotemporal dementia and healthy controls." (PMID 35769604, 2022). "Recently, neuronally derived exosomes in blood were found to contain elevated concentrations of CTSD, LAMP1, and ubiquitinated proteins already at a preclinical stage of AD, compared to controls and subjects with frontotemporal lobar degeneration." (PMID 31521194, 2019). "Impaired lysosomal proteolysis and decreased activity of the lysosomal enzyme cathepsin D were reported in fibroblasts lysates in heterozygous GRN mutation carriers and in iPSC-derived human cortical neurons in frontotemporal dementia (FTD) patients harboring GRN mutations." (PMID 36142612, 2022).
lung carcinoma (6 papers, 2009 to 2022). "Cathepsin D (CTSD) plays a decisive role in bone metastasis in lung cancer by degrading basement membrane components and the ECM." (PMID 32244796, 2020). "Cotreatment of PC (20 μM) or U0126 (20 μM) revealed had a greater inhibitory effect on CTSD expression and invasive motility in human A549 lung cancer cells." (PMID 32244796, 2020). "CTSD has been shown to be instrumental in lung cancer cell migration and invasion." (PMID 32244796, 2020). "To identify the effect of PC on the gene and protein expression of CTSD in NSCLC cells, we treated human A549 lung cancer cells with various concentrations (0, 10, 20, and 30 μM) of PC for 24 h, followed by immunoblotting and RT-qPCR assays." (PMID 32244796, 2020). "The decrease in cathepsin B and cathepsin D activities without any effects on autophagosome-lysosome fusion increases the cytotoxicity of cisplatin and paclitaxel in the lung cancer cells." (PMID 35387352, 2022). "Similarly, cellular proliferation and growth in soft agar were significantly compromised when lung cancer cells were cotreated with the Ang II synthesis inhibitors antipain and PPACK, which we show inhibit cathepsin D and TPA activity, respectively." (PMID 33380422, 2021). "Interestingly, cathepsin D and TPA, but not chymase, renin and ACE (not shown), were expressed in both A549 and H460 lung cancer cells and TPA levels were upregulated in NSCLC cells, as compared with NHBE cells." (PMID 33380422, 2021).
metastatic tumors (6 papers, 2009 to 2023). "Cathepsin D levels were associated with established features of tumour aggressiveness, such as positive lymph nodes, sarcomatoid change and metastatic disease at presentation as well as CT-defined tumour and overall stage." (PMID 19789534, 2009). "Again, increased levels of cathepsin D in primary and metastatic tumors in luminal B subtype have revealed that the cathepsin D expression pattern is a critical biological cell event associated with local recurrence and metastasis." (PMID 32846884, 2020). "Elevated cathepsin B (CTSB) and cathepsin D (CTSD) levels were detected in primary and metastatic tumor tissues of various cancer types." (PMID 26995190, 2016). "Patients with nodal/metastatic disease or sarcomatoid change had significantly higher median urinary cathepsin D levels." (PMID 19789534, 2009).
osteosarcoma (6 papers, 2015 to 2022). A usually aggressive malignant bone-forming mesenchymal neoplasm, predominantly affecting adolescents and young adults. "Even though no functional study of cathepsin D has been performed in osteosarcoma, our earlier work in proteome data mining suggests that cathepsin D is a potential biomarker and target for osteosarcoma treatment." (PMID 36077137, 2022). "The overexpression of cathepsin D was further confirmed by subsequent experiments in osteosarcoma cell culture and tissue samples." (PMID 36077137, 2022). "Overexpression of cathepsin D was also observed in osteosarcoma cells cultured in a spheroid form, where the osteosarcoma cells developed doxorubicin resistance compared to osteosarcoma cells cultured in the monolayer." (PMID 36077137, 2022). "CTSD expression reached significance between fetal osteoblasts and osteosarcomas (p = 0.0061), between fetal osteoblasts and pulmonary metastases (p = 0.0045) as well as between all three groups (p = 0.0127)." (PMID 26203049, 2015). "To confirm a higher expression of CTSD in pulmonary metastases compared to normal bone tissue and osteosarcomas, we build a customized TMA of 26 samples." (PMID 26203049, 2015). "For CTSD, the median cytoplasmatic immunopositivity (IP) was 0.0586 in fetal osteoblasts, 0.3886 in osteosarcomas and 0.5046 in pulmonary metastases." (PMID 26203049, 2015). "Through IHC scoring, CTSD expression was confirmed as increased in osteosarcoma relative to normal bone, and furthermore was significantly higher in pulmonary metastatic lesions than in primary-site osteosarcoma." (PMID 31722230, 2020). "As such, CTSD expression was revealed as a consistent differentiator between all three groups, and has been hypothesised as a driver of osteosarcoma oncogenesis and metastasis." (PMID 31722230, 2020). "In line with 2-DE and WB profiling, TMA-based immunohistochemistry revealed that CTSD was increased in osteosarcomas (p = 0.0237) and pulmonary metastases (p = 0.0079) compared to normal bone tissue and showed a significant regulation in the three group comparison (p = 0.0391)." (PMID 26203049, 2015). "However, this is the first report describing increased expression of CTSD in osteosarcomas, its pulmonary metastases and other bone disorders in general." (PMID 26203049, 2015). "Remarkably, a subsequent evaluation of a commercially available TMA of different bone entities (n = 176 tissues) showed the clinical impact of CTSD: CTSD immunostaining was located in the cytoplasm and showed a strong overexpression in osteosarcomas compared to osteocytes." (PMID 26203049, 2015). "In osteosarcoma, cathepsin D might play an essential role in metastasis and chemoresistance." (PMID 36077137, 2022). "In addition to being a marker for metastatic lesions, therapeutic targeting of CTSD may be a promising, novel avenue for osteosarcoma treatment which may yield favourable responses in metastatic disease." (PMID 31722230, 2020). "CTSD expression was further validated by IHC in a tumour microarray (TMA) comprising 4 normal bone tissue samples, 17 osteosarcoma samples, and 5 osteosarcoma pulmonary metastasis samples." (PMID 31722230, 2020). "Two proteins were increased (GLO1, CTSD) and the other two were decreased (RANBP1, STMN1) in osteosarcomas and metastases based on the 2-DE expression profile." (PMID 26203049, 2015). "In summary, our clinical proteomics workflow identified CTSD as an over-expressed protein in osteosarcomas and pulmonary metastases and may thus serve as a new biomarker for individualized treatment regimes for patients with osteosarcomas, even at metastastic stage." (PMID 26203049, 2015). "Expression of cathepsin D at both mRNA and protein levels was increased in highly metastatic osteosarcoma cells compared to non-metastatic cells." (PMID 36077137, 2022).
osteosarcoma (continued). "The results from immunohistochemistry of tissue microarrays demonstrated the overexpression of cathepsin D in lung metastases and osteosarcoma tissues compared to normal bone tissues." (PMID 36077137, 2022). "CTSD enhances the proliferation and invasiveness of NSCLC cells CTSD was validated in a clinical study and could acts as a biomarker for osteosarcomas, pulmonary metastasis, and bone malignancies." (PMID 32244796, 2020). "In detail, CTSD showed 0.2234 immunopositivity in osteosarcomas compared to no staining in all of the detected osteocytes (p < 0.0001) and 0.0450 immunopositivity in normal bone tissue (p = 0.0010)." (PMID 26203049, 2015).
triple-negative breast carcinoma (6 papers, 2013 to 2025). An invasive breast carcinoma which is negative for expression of estrogen receptor (ER), progesterone receptor (PR), and human epidermal growth factor receptor 2 (HER2). "We speculate that interrupted autophagy and ER stress are the possible mechanisms by which CTSD affects the function and activity of CD8+T cells in triple negative breast cancer." (PMID 40861815, 2025).
Batten disease (5 papers, 2021 to 2025). "One cellular phenotype observed in Batten disease is decreased cathepsin D (CtsD) activity, and CLN10 Batten disease is actually caused by mutations in CTsD itself." (PMID 38195117, 2024). "Commonly known as Batten disease, the different subtypes are each caused by a mutation in a distinct ceroid lipofuscinosis neuronal (CLN) gene (PPT1/CLN1, TPP1/CLN2, CLN3, DNAJC5/CLN4, CLN5, CLN6, MFSD8/CLN7, CLN8, CTSD/CLN10, PGRN/CLN11, ATP13A2/CLN12, CTSF/CLN13)." (PMID 35252181, 2022).